HYAL4 (hyaluronidase 4)
Description:
Endo-hyaluronidase that degrades hyaluronan to smaller oligosaccharide fragments. Also has chondroitin sulfate hydrolase activity, The best substrate being the galactosaminidic linkage in the sequence of a trisulfated tetrasaccharide.
Synonyms: Hyal-4; CSHY
Tractability: Antibody: UniProt predicts a signal peptide or a membrane-spanning region.
Gene: Protein-coding gene on chromosome 7 (123,828,955 to 123,877,481, forward strand). Ensembl gene ENSG00000106302.
Subcellular location: Membrane
Pathways (Reactome):
Metabolism: CS/DS degradation; Hyaluronan degradation
Gene Ontology:
Molecular function: chondroitin hydrolase activity; protein binding; hyalurononglucosaminidase activity
Biological process: chondroitin sulfate proteoglycan catabolic process; glycosaminoglycan catabolic process; hyaluronan catabolic process; carbohydrate metabolic process
Cellular component: lysosome; cytoplasmic vesicle; lysosomal lumen; cell surface; membrane
Genetic constraint (gnomAD): Loss-of-function variants: 33 observed, 32.67 expected, observed/expected ratio (o/e) 1.01, 90% interval 0.76 to 1.35. The upper end of that interval is the gene's LOEUF score, 1.35, which puts it in group 5 of 6, group 1 being the genes least tolerant of losing a copy. Missense variants: 526 observed, 555 expected, observed/expected ratio (o/e) 0.95, 90% interval 0.88 to 1.02. Synonymous variants: 184 observed, 197.51 expected, observed/expected ratio (o/e) 0.93, 90% interval 0.82 to 1.05.
Homologues: Orthologues: chimpanzee HYAL4 (98% identical), macaque HYAL4 (96% identical), rabbit HYAL4 (89% identical), dog HYAL4 (88% identical), pig HYAL4 (88% identical), mouse Hyal4 (80% identical), rat Hyal4 (78% identical), guinea pig HYAL4 (75% identical), zebrafish hyal4 (55% identical), Caenorhabditis elegans chhy-1 (26% identical). Paralogues in human: SPAM1 (42% identical), HYAL2 (37% identical), HYAL1 (36% identical), HYAL3 (32% identical).
Diseases named in the same sentence as HYAL4 in open-access papers:
HYAL4 is named in the same sentence as 21 diseases in open-access papers, as found by Europe PMC text mining. Sharing a sentence is not in itself a finding about the gene and the disease. The quoted sentences say what the papers report.
bladder cancer (2 papers, 2021 to 2022). "The v1 protein variant also showed chemotherapeutic resistance to Gemcitabine in preclinical models, suggesting HYAL4 drives chemoresistance in bladder cancer." (PMID 34746156, 2021). "In bladder cancer, HYAL4 activity increased the release of CD44, MMP-9 and Akt signalling and corresponded with metastasis and/or death of the patient after follow up." (PMID 34746156, 2021).
kidney cancer (2 papers, 2021 to 2022). Primary or metastatic malignant neoplasm involving the kidney. "In addition, mutations in the HYAL4 gene have been reported for some cancers including colorectal, stomach, lung, bladder, glioblastoma, leukemia, head/neck, ovarian, breast, and kidney cancers." (PMID 36144836, 2022). "Importantly, changes in HYAL4 expression changes in human disease have been described for testicular, bladder and kidney cancers, with gene mutations reported for several others including: leukaemia, endometrial, ovarian, colorectal, head and neck, stomach, lung and breast cancers." (PMID 34746156, 2021). "In kidney cancer tissue, HYAL4 mRNA expression was significantly increased in clear cell renal cell carcinomas, papillary tumours and chromophobe renal cell carcinomas when compared with oncocytomas and HYAL4 upregulation was increased in patients with metastasis." (PMID 34746156, 2021).
leukaemia (2 papers, 2021 to 2022). "Other cancers with HYAL4 gene mutations included: colorectal, stomach, lung (adenocarcinoma, squamous), bladder, glioblastoma, leukaemia, head/neck, ovarian, breast and kidney (clear cell) cancers (∼0.25–1.8% prevalence)." (PMID 34746156, 2021).
endometrial tumors (1 paper, 2022). "Maciej-Hulme roughly calculated that 4% of endometrial tumors have mutations in the HYAL4 gene." (PMID 36144836, 2022).
endometrioid carcinoma (1 paper, 2022). "HYAL4 had a positive influence on patients in staging III + IV for OS and PH20 for patients with an endometrioid carcinoma for PFS." (PMID 35767191, 2022).
glioma (1 paper, 2023). A benign or malignant brain and spinal cord tumor that arises from glial cells (astrocytes, oligodendrocytes, ependymal cells). "In TCGA and GEPIA databases, we found that among the 6 human hyaluronidases (HYAL1, HYAL2, HYAL3, HYAL4, HYALP1, SPAM1), only HYAL2 expression was highest in glioma." (PMID 37568202, 2023). "In the present study, our results confirmed that among the six hyaluronidases (HYAL1, HYAL2, HYAL3, HYAL4, HYALP1, SPAM1), only HYAL2 was overexpressed in glioma patients, and HYAL2 overexpression was negatively correlated with the survival time of glioma patients." (PMID 37568202, 2023).
melanoma (1 paper, 2025). A malignant, usually aggressive tumor composed of atypical, neoplastic melanocytes. "Hyal4 expression was weakly detected in melanoma cells and melanocytes and became slightly augmented by PACAP addition." (PMID 41465475, 2025).
osteoarthritis (1 paper, 2021). A noninflammatory degenerative joint disease occurring chiefly in older persons, characterized by degeneration of the articular cartilage, hypertrophy of bone at the margins and changes in the synovial membrane. "For example, 3B3- associated diseases such as osteoarthritis, development and aging warrant HYAL4 investigation." (PMID 34746156, 2021).
ovarian carcinoma (1 paper, 2022). A malignant neoplasm originating from the surface ovarian epithelium. "HAS1, HYAL1 and HYAL4 mRNA expression is significantly upregulated, whereas HAS2, HYAL2 and HYAL3 mRNA expression is significantly downregulated in ovarian cancer tissue compared to controls." (PMID 35767191, 2022). "Our TNMplot analysis of over 700 ovarian cancer specimens revealed that HAS1, HYAL1 and HYAL4 mRNA expression is significantly upregulated, whereas HAS2, HYAL2 and HYAL3 mRNA expression is significantly downregulated in ovarian cancer tissue compared to controls." (PMID 35767191, 2022).
testicular cancer (1 paper, 2021). A primary or metastatic malignant neoplasm that affects the testis.
tumor (6 papers, 2013 to 2025). "Notably, the commonality of HYAL4 shared between cancer proliferation and stem cell naivety points toward a function for HYAL4 in the development and/or maintenance of cancer stem cells, which often cause therapeutic resistance and tumour relapse." (PMID 34746156, 2021). "In tumour tissue, all samples showed HYAL4 expression, with low expression in 8 samples and medium expression in 3 probes." (PMID 35767191, 2022). "Hyal4’s specific contribution to tumour progression is still under investigation, but it may influence tumour cell interactions with the microenvironment through modulation of glycosaminoglycan composition." (PMID 41465475, 2025). "Subsequently, we confirmed well-characterized oncogenes among tumor-related loci (such as EGFR and KIT) and detected novel genes that gained chromosome sequences (such as AASS, HYAL4, NDUFA5 and SPAM1) in both LGG and HGG." (PMID 23451178, 2013). "Interestingly, in our system, significantly increased expression of synthases (HAS2, HAS3) and hyaluronidases (HYAL1, HYAL3, HYAL4) was detected in the tumor cells but not in the stromal portion of TW2.6 tumors." (PMID 34869001, 2021).
cancer (5 papers, 2021 to 2024). A tumor composed of atypical neoplastic, often pleomorphic cells that invade other tissues. "So far, only two of the HYAL4 mutated cancer types identified have been investigated in more detail." (PMID 34746156, 2021). "In the Cancer Genome Atlas project database, HYAL4 gene mutations were associated with 12 out of the 15 cancer types analysed." (PMID 34746156, 2021). "Together, these data suggest that a defective HYAL4 mechanism may underlie the formation of various cancers." (PMID 34746156, 2021). "High expression of HYAL4 in some cancer tissues and cells has been reported." (PMID 36144836, 2022). "It is necessary to investigate the mechanism linking HYAL4 to cancer." (PMID 36144836, 2022). "Hyal4 may be involved in cancer invasion and metastasis by degrading CS-proteoglycans in the extracellular matrix." (PMID 36144836, 2022). "On a protein level, interaction of HYAL4 with NEK4 may play an important part in the epithelial-to-mesenchymal transition of cells during the development of cancer." (PMID 34746156, 2021). "Thus, swift investigation of HYAL4 in more cancers could provide beneficial insight and a novel, specific treatment target for a variety of cancer patients." (PMID 34746156, 2021).
HYAL4 also shares sentences with these, for which no sentence is quoted: psoriasis (2 papers); autism spectrum disorder (1); breast carcinoma (1); chromophobe renal cell carcinoma (1); clear cell renal cell carcinomas (1); diffuse large B-cell lymphoma (1); glioblastoma (1); oncocytomas (1); Stroke (1).